MIR210HG (MIR210 host gene)
Gene: Long non-coding RNA gene on chromosome 11 (565,657 to 568,542, reverse strand). Ensembl gene ENSG00000247095.
Diseases named in the same sentence as MIR210HG in open-access papers:
MIR210HG is named in the same sentence as 19 diseases in open-access papers, as found by Europe PMC text mining. Sharing a sentence is not in itself a finding about the gene and the disease. The quoted sentences say what the papers report.
glioma (7 papers, 2019 to 2024). A benign or malignant brain and spinal cord tumor that arises from glial cells (astrocytes, oligodendrocytes, ependymal cells). "The overexpression of MIR210HG has been linked to unfavorable clinical outcomes in several cancer types, including glioma, endometrial cancer, and lung cancer." (PMID 38907744, 2024). "For example, HIF1α was found to orchestrate regeneration resistance by upregulating AMPK-mediated ATM expression in severe hypoxia, while it promotes glioma invasion and stem cell formation by regulating MIR210HG and OCT1." (PMID 38893207, 2024). "Previous reports have shown that MIR210HG is a ceRNA sponge for miRNAs, thereby de-repressing the target genes of these miRNAs in glioma and colorectal adenocarcinoma." (PMID 31399552, 2019). "MIR210HG is elevated in a variety of tumors such as cervical cancer, non-small cell lung cancer, breast cancer, colorectal adenocarcinoma, pancreatic cancer, liver cancer, osteosarcoma, and glioma." (PMID 35431958, 2022). "A nine-EMT-related lncRNAs (HAR1A, LINC00641, LINC00900, MIR210HG, MIR22HG, PVT1, SLC25A21-AS1, SNAI3-AS1, and SNHG18) signature was identified in patients with glioma." (PMID 34288803, 2021). "Previously, MIR210HG has been demonstrated to be overexpressed in hepatocellular carcinoma, non-small cell lung cancer (NSCLC), osteosarcoma, glioma and chemoresistant pancreatic cancer." (PMID 33392077, 2020). "Among the nine EMT-related lncRNAs identified in this study, LINC00900, MIR210HG, MIR22HG, PVT1, and SNHG18 were positively correlated with glioma malignancy, whereas HAR1A, LINC00641, SLC25A21-AS1, and SNAI3-AS1 were negatively correlated with glioma malignancy." (PMID 34288803, 2021).
cervical cancer (6 papers, 2020 to 2024). A primary or metastatic malignant neoplasm involving the cervix. "Further, MIR210HG upregulation has been shown to be associated with advanced International Federation of Gynecology and Obstetrics stage, metastasis, and poor prognosis in cervical cancer." (PMID 34288803, 2021). "MIR210HG has been experimentally demonstrated to promote proliferation and invasion of tumor cells in hepatocellular carcinoma, non-small-cell lung cancer, breast cancer, cervical cancer, osteosarcoma, and other tumors." (PMID 32596355, 2020). "In this study, MIR210HG was identified as a protective factor, and it has been reported to promote tumour progression in endometrial cancer, non-small cell lung cancer, triple-negative breast cancer, cervical cancer, colorectal cancer, and hepatocellular carcinoma 34-41." (PMID 35517417, 2022). "In cervical cancer, phosphoglycerate kinase 1 (PGK1) promotes tumor growth, and MIR210HG may promote PGK1 expression." (PMID 38706901, 2024).
breast carcinoma (5 papers, 2019 to 2022). "In summary, MIR210HG functions as an oncogenic lncRNA in breast cancer, which is also mediated by its encoded miR-210." (PMID 35346372, 2022). "Collectively, miR-210 is an effector of MIR210HG and mediates MIR210HG function in breast cancer progression." (PMID 35346372, 2022). "In following step, we determined the function of MIR210HG in migration and invasion of breast cancer cells." (PMID 35346372, 2022). "Collectively, MIR210HG is an oncogenic lncRNA, which is possibly involved in breast cancer progression." (PMID 35346372, 2022). "More importantly, its encoded miR-210 mediated MIR210HG function, which suggests that MIR210HG/miR-210 axis is critical in breast cancer progression." (PMID 35346372, 2022). "To determine the expression levels of MIR210HG in breast cancer cell lines, we found that 14 IBC cell lines showed various expression levels of MIR210HG in TCGA cell line database." (PMID 31399552, 2019). "High expression of MIR210HG was observed in breast cancer in all selected datasets." (PMID 35346372, 2022). "Taken together, MIR210HG promotes breast cancer proliferation." (PMID 35346372, 2022). "Therefore, MIR210HG induces migration and invasion of breast cancer cells by regulating EMT process." (PMID 35346372, 2022). "In addition to pancreatic cancer, MIR210HG can also promote various cancer types, such as breast cancer, gastric cancer, and ovarian cancer." (PMID 36203430, 2022). "In breast cancer, MIR210HG is involved in Warburg Effect that induces tumor growth." (PMID 35346372, 2022). "Conversely, ectopic MIR210HG enhanced the colony forming capacity of breast cancer cells." (PMID 35346372, 2022). "Silencing MIR210HG repressed proliferation of breast cancer cells, whereas DOX induced MIR210HG increased breast cancer cell proliferation." (PMID 35346372, 2022).
pancreatic cancer (4 papers, 2019 to 2022). "A coexpression network revealed a hub comprising lncRNAs (MIR210HG, SNHG1, and LOC729970) and mRNAs (RAB3D, DDX17, and SPNS2) that presumably mediate drug resistance in pancreatic cancer." (PMID 31399552, 2019).
ovarian carcinoma (2 papers, 2021 to 2022). A malignant neoplasm originating from the surface ovarian epithelium. "Knockdown of VHL also efficiently blocked shMIR210HG-mediated HIF-1α reduction in ovarian cancer cells, which suggested that MIR210HG regulates HIF-1α expression in a VHL-dependent manner." (PMID 34900667, 2021). "Our study first determined the function of MIR210HG in ovarian cancer and confirmed the promoting role of MIR210HG in EMT and tumor angiogenesis in ovarian cancer." (PMID 34900667, 2021).
glioblastoma multiforme (1 paper, 2023). "LncRNA MIR210HG interacted with octamer transcription factor 1, promoting FGFR1 transcription and glioblastoma multiforme progression." (PMID 37993879, 2023).
tumor (11 papers, 2020 to 2024). "Through sponging miRNAs, MIR210HG promotes tumor proliferation, metastasis and in some cases, is involved in energy metabolism in cancer." (PMID 35346372, 2022). "Previous studies have shown that MIR210HG acts as an oncogene and promotes tumor progression." (PMID 38474063, 2024). "Previous studies reveal that MIR210HG functions as an oncogene and promotes tumor progression." (PMID 35346372, 2022). "Elevated levels of MIR210HG expression have been found in other cancers, with its higher levels reported in hepatocellular carcinoma tissue, which correlates with the clinical stage of the disease and tumour characteristics, including size, vascular invasion, and histological differentiation." (PMID 38790894, 2024). "Thus, we provided a previous unprecedented mechanism by which MIR210HG promotes tumor progression." (PMID 33392077, 2020). "MIR210HG is highly expressed in NSCLC tissues and its expression is correlated with tumor stage and lymph node metastasis in NSCLC patients." (PMID 34900667, 2021). "LINC00900, MIR210HG, MIR22HG, PVT1, and SNHG18 expression increased, whereas HAR1A, LINC00641, SLC25A21-AS1, and SNAI3-AS1 expression decreased with tumor grade." (PMID 34288803, 2021).
cancer (6 papers, 2019 to 2024). A tumor composed of atypical neoplastic, often pleomorphic cells that invade other tissues. "Of note, pan-cancer analysis indicated MIR210HG was highly expressed in most cancer types, suggesting that MIR210HG is an oncogene and promising target for cancer therapy." (PMID 35346372, 2022). "To evaluate the oncogenic role of MIR210HG in multiple cancer types, we analyzed the pan-cancer dataset from the TCGA database." (PMID 31399552, 2019). "Actually, MIR210HG has been reported to function as an oncogene in different cancers." (PMID 35346372, 2022). "MIR210HG was also an important regulator of cell proliferation and invasion in diverse cancers." (PMID 34900667, 2021). "Recently, there are some reports about the roles of MIR210HG in human cancers." (PMID 32087604, 2020).
MIR210HG also shares sentences with these, for which no sentence is quoted: non-small cell lung carcinoma (4 papers); osteosarcoma (4); hepatocellular carcinoma (3); colorectal adenocarcinoma (2); colorectal cancer (2); endometrial cancer (2); triple-negative breast carcinoma (2); breast tumor (1); gastric cancer (1); liver cancer (1); lung carcinoma (1).